RAB11FIP4 (RAB11 family interacting protein 4)
Description:
Acts as a regulator of endocytic traffic by participating in membrane delivery. Required for the abscission step in cytokinesis, possibly by acting as an 'address tag' delivering recycling endosome membranes to the cleavage furrow during late cytokinesis. In case of infection by HCMV (human cytomegalovirus), may participate in egress of the virus out of nucleus; this function is independent of ARF6.
Synonyms: FIP4-Rab11; Rab11-FIP4; KIAA1821; MGC11316; FLJ00131
Tractability: Antibody: UniProt places it where antibodies can reach, with medium confidence. PROTAC: ubiquitination databases record sites on it.
Gene: Protein-coding gene on chromosome 17 (31,391,675 to 31,538,211, forward strand). Ensembl gene ENSG00000131242.
Subcellular location: Endosome; Cytoplasm, cytoskeleton, spindle; Cytoplasm, cytoskeleton, microtubule organizing center, centrosome; Recycling endosome membrane; Cleavage furrow; Midbody; Cytoplasmic vesicle
Subcellular location (Human Protein Atlas): Connecting piece; Golgi apparatus; Mid piece; Vesicles; Principal piece
Gene Ontology:
Molecular function: protein binding; protein homodimerization activity; small GTPase binding; calcium ion binding
Biological process: regulation of cytokinesis; endocytic recycling
Cellular component: cleavage furrow; cytoplasmic vesicle; endocytic vesicle; endosome; extracellular region; midbody; recycling endosome membrane; centrosome; perinuclear region of cytoplasm; spindle
Genetic constraint (gnomAD): Loss-of-function variants: 23 observed, 60.83 expected, observed/expected ratio (o/e) 0.38, 90% interval 0.27 to 0.54. The upper end of that interval is the gene's LOEUF score, 0.54, which puts it in group 2 of 6, group 1 being the genes least tolerant of losing a copy. Missense variants: 625 observed, 792.98 expected, observed/expected ratio (o/e) 0.79, 90% interval 0.74 to 0.84. Synonymous variants: 357 observed, 328.03 expected, observed/expected ratio (o/e) 1.09, 90% interval 1 to 1.19.
Homologues: Orthologues: chimpanzee RAB11FIP4 (100% identical), dog RAB11FIP4 (95% identical), pig RAB11FIP4 (94% identical), macaque RAB11FIP4 (94% identical), rat Rab11fip4 (93% identical), mouse Rab11fip4 (93% identical), guinea pig RAB11FIP4 (86% identical), rabbit RAB11FIP4 (86% identical), zebrafish rab11fip4a (69% identical), tropical clawed frog rab11fip4 (54% identical), zebrafish rab11fip4b (52% identical), Drosophila melanogaster nuf (19% identical), and 1 more. Paralogues in human: RAB11FIP3 (39% identical).
Diseases named in the same sentence as RAB11FIP4 in open-access papers:
RAB11FIP4 is named in the same sentence as 2 diseases in open-access papers, as found by Europe PMC text mining. Sharing a sentence is not in itself a finding about the gene and the disease.
RAB11FIP4 shares sentences with these, for which no sentence is quoted: cancer (1 paper); pertussis (1).